SPRR4 (small proline rich protein 4)
Description:
Cross-linked envelope protein of keratinocytes. Involved in UV-induced cornification.
Tractability: No criterion of Open Targets' tractability assessment is met for any kind of drug.
Gene: Protein-coding gene on chromosome 1 (152,970,648 to 152,972,574, forward strand). Ensembl gene ENSG00000184148.
Subcellular location: Cytoplasm; Cytoplasm, cell cortex
Subcellular location (Human Protein Atlas): Cytosol; Nucleoplasm; Nuclear membrane
Gene Ontology:
Cellular component: cytosol; cell cortex; cytoplasm
Genetic constraint (gnomAD): Loss-of-function variants: 0 observed, 2.87 expected, observed/expected ratio (o/e) 0, 90% interval 0 to 1.02. That is too few expected variants to judge how well the gene tolerates losing a copy. Missense variants: 106 observed, 96.03 expected, observed/expected ratio (o/e) 1.1, 90% interval 0.94 to 1.3. Synonymous variants: 30 observed, 36.26 expected, observed/expected ratio (o/e) 0.83, 90% interval 0.62 to 1.12.
Homologues: Orthologues: rat Sprr4 (72% identical), mouse Sprr4 (70% identical). Paralogues in human: SPRR1A (58% identical), SPRR1B (58% identical), SPRR3 (52% identical), SPRR2G (39% identical), PRR9 (34% identical), KPLCE (30% identical), LCE5A (28% identical), LCE1E (25% identical), LCE1F (25% identical), LCE2A (25% identical), LCE2B (25% identical), LCE2C (25% identical), and 8 more.